SNORA24 (small nucleolar RNA, H/ACA box 24)
Synonyms: ACA24; SNORA24A
Gene: Small nucleolar RNA gene on chromosome 4 (118,279,190 to 118,279,320, forward strand). Ensembl gene ENSG00000275994.
Gene Ontology:
Biological process: RNA processing
Cellular component: nucleolus
Homologues: Orthologues: chimpanzee SNORA24 (100% identical), rabbit SNORA24 (98% identical), macaque SNORA24 (98% identical), guinea pig SNORA24 (97% identical), pig SNORA24 (97% identical), mouse Snora24 (91% identical), rat LOC120101240 (91% identical), rat LOC120100362 (89% identical). Paralogues in human: SNORA24B (94% identical).
Diseases named in the same sentence as SNORA24 in open-access papers:
SNORA24 is named in the same sentence as 6 diseases in open-access papers, as found by Europe PMC text mining. Sharing a sentence is not in itself a finding about the gene and the disease. The quoted sentences say what the papers report.
hepatocellular carcinoma (5 papers, 2019 to 2022). A malignant tumor that arises from hepatocytes. "Accordingly, in a recent study, McMahon and others characterized the role of SNORA24 in hepatocellular carcinoma and its cooperation with oncogenic RAS mutations." (PMID 35719370, 2022). "We find that in mouse models, loss of Snora24 cooperates with RASG12V to promote the development of liver cancer that closely resembles human steatohepatitic hepatocellular carcinoma (HCC)." (PMID 31478838, 2019). "The gene specific contribution of H/ACA snoRNAs to tumour aggressiveness is also evident from a previous study showing that SNORA24 may function as a suppressor of hepatocellular carcinoma and its reduced expression is associated with poor prognosis of hepatocellular carcinoma." (PMID 35047824, 2022). "SNORA24, which mediates two distinct pseudouridine modifications in the small, 40S subunit of the ribosome is also decreased in human hepatocellular carcinoma (HCC)." (PMID 31478838, 2019). "Snora24 plays a role in the initiation and maintenance of RAS-driven hepatocellular carcinoma." (PMID 31478838, 2019).
liver cancer (2 papers, 2019 to 2022). An epithelial or non-epithelial malignant neoplasm that arises from the liver. "As SNORA24 was significantly decreased in HCC and low SNORA24 levels were associated with poor patient survival, we next sought to assess the tumor suppressor activity of Snora24 in liver cancer development in vivo." (PMID 31478838, 2019). "We further show that loss of Snora24 cooperates with RASG12V to promote the development of liver cancer in vivo resembling a subtype of HCC characterized by lipid deposition, with similar features, as described in human steatohepatitic HCC (SH-HCC)." (PMID 31478838, 2019). "Snora24 reduction in this mouse model of liver cancer significantly decreased Snora24-guided pseudouridine modifications on 18S rRNA as shown using SCARLET (Site-specific Cleavage And Radioactive-labeling followed by Ligation-assisted Extraction and Thin-layer chromatography)." (PMID 31478838, 2019). "To investigate the importance of Snora24 in established HCC, we turned to a genetically engineered mouse model of liver cancer driven by the expression of oncogenic KrasG12D in the mouse liver using albumin-cre (Alb-cre;KrasG12D)." (PMID 31478838, 2019). "Given that loss of Snora24 cooperates with oncogenic RAS to promote the development of liver cancer resembling human SH-HCC, we sought to explore the clinical relationship between SNORA24 expression and lipid content in human HCC." (PMID 31478838, 2019).
dyskeratosis congenita (1 paper, 2021). Dyskeratosis congenita (DC) is a rare ectodermal dysplasia that often presents with the classic triad of nail dysplasia, skin pigmentary changes, and oral leukoplakia associated with a high risk of bone marrow failure (BMF) and cancer. "Down-regulation of box H/ACA snoRNAs (such as SNORA15 and SNORA24) has been associated with human diseases including dyskeratosis congenita and leukemia." (PMID 33561224, 2021).
tumor (7 papers, 2019 to 2025). "Acting as a tumor suppressor, SNORA24 is down-regulated in HCC and its low levels were associated with decreased survival." (PMID 36078062, 2022). "Our studies reveal that SNORA24 is implicated in a tumor suppressor program in vivo to halt cellular transformation and with compelling human and mouse data supports a role for SNORA24 dysfunction in tumor initiation and in maintenance of RAS-driven cancer." (PMID 31478838, 2019). "One intriguing possibility is that SNORA24-guided modifications directly impinge on the production of proteins involved in, for example, lipid metabolism and signaling, due to the strong association between SNORA24 and tumor lipid deposition identified in this study." (PMID 31478838, 2019). "A low level of SNORA24 played a critical role in tumor initiation and progression and in the ability to evade the tumor-suppressive defense mechanism conferred by OIS." (PMID 36078062, 2022). "Similar to our observations from microarray gene expression analysis, SNORA24 was dramatically decreased in all HCC tumor specimens compared to non-tumor adjacent tissue by qPCR (p<0.0001)." (PMID 31478838, 2019). "In line with human HCC patient expression data, we found that in established liver tumors derived from Alb-cre;KrasG12D mice, Snora24 was significantly decreased in tumor tissue compared to liver tissue from wild-type mice (n = 3 mice per condition)." (PMID 31478838, 2019). "In a hepatocellular carcinoma model driven by oncogenic RAS, McMahon and colleagues demonstrated that this loss of translational fidelity enables cells to bypass oncogene-induced senescence, thereby allowing tumor development and validating SNORA24 as tumor suppressor." (PMID 41375049, 2025). "SNORA24 has been found to be required for oncogene-induced senescence and tumor suppression." (PMID 38345344, 2024). "The study revealed that SNORA24 levels, which mediates two distinct pseudouridine modifications in the small 40S subunit of the ribosome, were decreased in HCC and is implicated in a tumour suppressor program that blocks cellular transformation." (PMID 35331312, 2022). "Moreover, human and mouse data support a role for SNORA24 dysfunction in tumour initiation and in maintenance of RAS-driven cancers." (PMID 35331312, 2022). "Together, these findings suggest that SNORA24 may exert a tumor suppressor role in HCC." (PMID 31478838, 2019). "For example, SNORA21, SNORA24, and SNORA42 are upregulated in CRC and promote tumor growth both in vivo and in vitro; SNORD1C maintains the stemness of CRC cells and resistance to the chemotherapeutic drug 5-FU by activating the Wnt pathway." (PMID 37907779, 2023). "All of these results indicated that the down-regulation of SNORA24 in HCC triggered aberrant lipid metabolism and promoted tumor formation and maintenance." (PMID 36078062, 2022). "Having identified that cancer-associated changes in Snora24 lead to bypass of OIS in the context of oncogenic RAS expression in vivo, we next sought to determine whether reduction of this single H/ACA snoRNA was sufficient to promote tumor development in this model." (PMID 31478838, 2019). "In the same matched tumor and adjacent non-tumor tissue, we detected no change in the expression of the SNORA24 host gene, SNHG8 (Small Nucleolar RNA Host Gene 8)." (PMID 31478838, 2019).
cancer (1 paper, 2019). A tumor composed of atypical neoplastic, often pleomorphic cells that invade other tissues. "Interestingly, in the context of HCC, SNORA24 appears dispensable for overall protein synthesis, suggesting that cancer-associated changes in SNORA24 may have more selective functions, for example towards controlling translation of specific mRNAs." (PMID 31478838, 2019).
SNORA24 also shares sentences with these, for which no sentence is quoted: leukemia (1 paper).